ENSG00000299462 (novel transcript, antisense to FAM172A)
Gene: Long non-coding RNA gene on chromosome 5 (94,041,878 to 94,045,329, forward strand). Ensembl gene ENSG00000299462.
Gene Ontology:
Biological process: SRP-dependent cotranslational protein targeting to membrane, signal sequence recognition
Cellular component: signal recognition particle, endoplasmic reticulum targeting